LINC02433 (long independently transcribed non-coding RNA 2433)
Gene: Long non-coding RNA gene on chromosome 4 (157,572,470 to 157,576,154, forward strand). Ensembl gene ENSG00000234111.
Diseases named in the same sentence as LINC02433 in open-access papers:
LINC02433 is named in the same sentence as 2 diseases in open-access papers, as found by Europe PMC text mining. Sharing a sentence is not in itself a finding about the gene and the disease.
LINC02433 shares sentences with these, for which no sentence is quoted: fibroids (2 papers); tumor (1).